OR5L2 (olfactory receptor family 5 subfamily L member 2)
Description:
Odorant receptor.
Synonyms: HTPCRX16; HSHTPCRX16; OR11-153
Tractability: Antibody: UniProt places it where antibodies can reach, with medium confidence; UniProt predicts a signal peptide or a membrane-spanning region; its Gene Ontology location is reachable by antibodies, with medium confidence.
Gene: Protein-coding gene on chromosome 11 (55,827,219 to 55,828,154, forward strand). Ensembl gene ENSG00000205030.
Subcellular location: Cell membrane
Pathways (Reactome):
Sensory Perception: Expression and translocation of olfactory receptors
Gene Ontology:
Molecular function: olfactory receptor activity; G protein-coupled receptor activity
Biological process: G protein-coupled receptor signaling pathway; sensory perception of smell; detection of chemical stimulus involved in sensory perception of smell
Cellular component: plasma membrane; membrane
Genetic constraint (gnomAD): Missense variants: 425 observed, 374.82 expected, observed/expected ratio (o/e) 1.13, 90% interval 1.05 to 1.23. Synonymous variants: 175 observed, 152.44 expected, observed/expected ratio (o/e) 1.15, 90% interval 1.01 to 1.3.
Homologues: Orthologues: chimpanzee OR5L2 (98% identical), macaque OR5L1 (89% identical), dog OR5L1 (82% identical), dog OR5L1C (81% identical), dog OR5L1B (79% identical), mouse Or5l14 (78% identical), rat Or5l13 (75% identical), mouse Or5l13 (74% identical), rat Or5l14b (74% identical). Paralogues in human: OR5L1 (92% identical), OR5D18 (61% identical), OR5D16 (58% identical), OR5D14 (56% identical), OR5I1 (54% identical), OR5AP2 (53% identical), OR5D3 (53% identical), OR5D13 (52% identical), OR5W2 (52% identical), OR8D1 (52% identical), OR9I1 (52% identical), OR5J2 (51% identical), and 84 more.